MAP3K1 (mitogen-activated protein kinase kinase kinase 1)
Diseases named in the same sentence as MAP3K1 in open-access papers (continued):
Sharing a sentence is not in itself a finding about the gene and the disease.
breast cancer (continued). "Grouped by gene, many of these novel mutations comprised large gains in absolute counts and in percent increase, including MAP3K1 and GATA3 in breast cancer, and NOTCH2 and CDKN2A in lung cancer." (PMID 24970867, 2014). "At the molecular level, we observed a reduced frequency of MAP3K1 mutations in kinase fusion-positive cases compared with that in fusion-negative cases, both in the overall cohort and in HR+/HER2‒ breast cancer." (PMID 41213951, 2025). "Moreover, in breast cancer, dysregulated expression of MAP3K genes, such as MAP3K1 and MAP3K7, promotes tumor growth, invasion, and metastasis through activation of MAPK and NF-κB signaling pathways, mirroring their roles in GC." (PMID 39901302, 2025). "MAP kinase MEKK1, coded by MAP3K1, has been reported to promote cancer cell migration by contributing to an accommodating breast tumor microenvironment, while FGFR2 has been identified as a viable drug target in breast cancer." (PMID 36703164, 2023). "Furthermore, subgrouping classifiers for breast cancer genes such as GATA3 and MAP3K1 which had been found to be divergent from the corresponding gene-wide classifiers preserved their divergence in the transfer setting." (PMID 33957863, 2021). "In ER+ breast cancer cell lines, siRNA-mediated knockdown of MAP3K1 did not affect the response to buparlisib." (PMID 31552290, 2019). "Several frequently mutated genes in breast cancer, such as CDH1, GATA3, and MAP3K1, were not mutated in any MPA/DMBA-induced tumors." (PMID 31366361, 2019). "Interestingly, module 5 (with Mucins) is mutually exclusive with many known breast cancer drivers including PIK3CA, MAP3K1, and RUNX1." (PMID 29023534, 2017). "Only rs889312 from the region near MAP3K1 was replicated, and without correction for multiple comparisons (P = 0.04 in CGEMS), with the suggestion of a slight increased risk of breast cancer (OR 1.15, 95% CI 1.01–1.30)." (PMID 23634849, 2013). "Genome-wide association studies (GWAS) have identified breast cancer susceptibility loci in or near genes such as FGFR2, TOX3 (formerly known as TNRC9), LSP1, HCN1/MRPS30, MAP3K1 and at 2q that had not previously been considered." (PMID 19232126, 2009). "In conclusion, our study demonstrated the ability of MAP3K1 to modulate the tumor microenvironment via regulation of tumor antigen presentation and highlighted the clinical potential of the postbiotic Tyra to enhance immunotherapy efficacy in HR+/HER2– breast cancer." (PMID 39531335, 2024). "Note that in the time course experiment using four breast cancer cell lines, the MEK inhibitor sensitivity of the two MAP2K4 mutant breast cancer cell lines was also not very apparent during the first 72 h of culture and similar result was seen in the isogenic MAP3K1 and MAP2K4 knockout cells." (PMID 29795445, 2018). "However, in basal‐like breast cancer, mutations in MAP3K1 or MAP2K4 are notably absent, suggesting that they may not provide similar increase in cellular fitness to what is observed in luminal breast cancer cells." (PMID 30190333, 2018). "Thus, Map3k1 amiRNA-3 may not influence the apoptotic response of breast cancer cells." (PMID 26759750, 2016).
breast tumors (17 papers, 2014 to 2024). "Based on published articles, mutation of MAP3K1 was potential drug targets in combination with MEK inhibitors in breast tumors." (PMID 34512634, 2021). "GATA3, ZNF703, and MAP3K1 are in the group 1 genes associated with acquired endocrine therapy resistance in breast tumors expressing ESR1 and ERBB2." (PMID 29738475, 2018). "A recent report from TCGA identified a hypermethylated, HR+ breast tumor subset with lower Wnt-pathway gene expression and fewer PIK3CA and MAP3K1 mutations." (PMID 25287138, 2014). "Administration of Tyra could reverse the downregulation of tumor antigen presentation caused by MAP3K1 mutation, thus promoting CD8+ T cell–mediated antitumor immunity and enhancing the efficacy of anti–PD-1 immunotherapy in HR+/HER2– breast tumors in vivo." (PMID 39531335, 2024). "Finally, the frequency of the top mutated cancer driver genes (>5%) in HM breast tumors varies among the evaluated ancestries, with PIK3CA, MAP3K1 and PTEN having the highest similarities." (PMID 33854067, 2021). "HER2-low breast tumors also had significantly higher mutations rates in CBFB (p < 0.05), PIK3CA (p < 0.05), mitogen-activated protein kinase kinase kinase 1 (MAP3K1; p < 0.05), and AT-rich interaction domain 1A (ARID1A; p < 0.05) as compared with HER2-zero breast tumors." (PMID 35484593, 2022).
ovarian carcinoma (14 papers, 2006 to 2023). A malignant neoplasm originating from the surface ovarian epithelium. "In the replication analysis, we found some shared genes in two independent cohorts, such as FGFR2 for the breast–ovarian cancer pair and MAP3K1 for the breast–lung cancer pair." (PMID 36819030, 2023). "Previous studies have demonstrated that MAP3K1 could trigger the transcriptional activities of the ERs in endometrial and ovarian cancer cells." (PMID 28178648, 2017). "We further performed correlation analysis of GPR12 mRNA level with ERK1/2 cascade expression including MAP3K1, MAP2K1, MAP2K2, and MAPK1 by using ovarian cancer data from TCGA database." (PMID 35903681, 2022).
glioma (12 papers, 2017 to 2025). A benign or malignant brain and spinal cord tumor that arises from glial cells (astrocytes, oligodendrocytes, ependymal cells). "All results indicate that the overexpression of MAP3K1 holds great potential as a diagnostic and prognostic biomarker for glioma and is significantly linked to the progression of the disease." (PMID 39443331, 2024). "Even though multiple datasets we performed have analysed the role of MAP3K1 in diagnosing and predicting the outcome of glioma, further research is required to conclusively establish MAP3K1 as a new diagnostic marker and prognostic indicator for glioma." (PMID 39443331, 2024). "Abnormal overexpression of MAP3K1 in glioma is strongly associated with unfavourable clinicopathological characteristics and disease progression." (PMID 39443331, 2024). "Several factors, including WHO grade, primary therapy outcome, age and MAP3K1 expression, were significantly associated with the OS of glioma patients." (PMID 39443331, 2024). "Collectively, the poor clinicopathological characteristics of glioma were significantly linked to the aberrant expression of MAP3K1." (PMID 39443331, 2024). "Our findings indicate that the overexpression of MAP3K1 serves as a promising diagnostic and prognostic biomarker for glioma." (PMID 39443331, 2024). "For gliomas, one recent study demonstrated that its combined elevated expression with MAP3K1 was significantly associated with survival and chemoresistance." (PMID 35044082, 2022). "MAP3K1 serves as a reliable diagnostic and prognostic biomarker for glioma." (PMID 39443331, 2024). "Our results indicate that MAP3K1 might be implicated in glioma progression and function as a promoter in glioma." (PMID 39443331, 2024). "Association between MAP3K1 mRNA expression and the clinical parameters of glioma patients in TCGA." (PMID 39443331, 2024). "In addition, we performed survival analysis including OS, PFI (progression‐free interval) and DSS (disease‐specific survival) and found that the expression of MAP3K1 was negatively associated with the prognosis of glioma." (PMID 39443331, 2024). "Extensive research has shown that MAP3K1 plays a crucial role in cell migration, growth, and apoptosis, and its dysregulation is closely associated with adverse outcomes in various malignancies, including glioma." (PMID 37662954, 2023). "MAP3K1 might promote glioma stem cell progression and be positively associated with resistance to temozolomide (TMZ) and radiotherapy." (PMID 35832194, 2022). "The results demonstrated that MAP3K1 is one of the most closely associated genes with TRIB2 in glioma, indicating that MAP3K1 might be functionally regulated by TRIB2 and could be used as a potential combined biomarker for glioma." (PMID 31318172, 2020). "Additionally, TRIB2 and MAP3K1 overexpression was associated with the histological grade of glioma (χ2 = 18.86, P < 0.01 for TRIB2 and χ2 = 38.06, P < 0.01 for MAP3K1)." (PMID 31318172, 2020). "MAP3K1 was proved to be associated with the pathological manifestations and survival of glioma." (PMID 33057597, 2020). "Moreover, a combined increase in TRIB2 and MAP3K1 in glioma is associated with a poor prognosis and therapeutic resistance to TMZ and radiotherapy." (PMID 31318172, 2020). "MAP3K1 could potentially serve as a reliable diagnostic and prognostic biomarker for glioma." (PMID 39443331, 2024). "MAP3K1 might be a promising diagnostic and prognostic biomarker for glioma." (PMID 39443331, 2024). "Correlated overexpression of TRIB2 and MAP3K1 could be associated with high‐grade glioma." (PMID 31318172, 2020). "Coincidentally, the top 25 genes positively correlated with MAP3K1 in the TCGA dataset were predominantly enriched in glioma cells." (PMID 39443331, 2024). "MAP3K1 knockdown exacerbated the temozolomide (TMZ) induced inhibition of glioma cell proliferation and death of GBM cells." (PMID 39443331, 2024).
glioma (continued). "To elucidate the role of MAP3K1 in glioma, we analysed genes that are co‐expressed with MAP3K1 in the TCGA dataset." (PMID 39443331, 2024). "A nomogram was constructed using Cox regression analysis to predict the survival probability of glioma patients at 1, 3 and 5 years based on MAP3K1 expression and clinicopathologic factors." (PMID 39443331, 2024). "From the CGGA datasets, we proceeded to validate the expression of MAP3K1 in various molecular subtypes and grades of glioma." (PMID 39443331, 2024). "MAP3K1 knockdown exacerbated the TMZ induced inhibition of glioma cell proliferation and increased the cell death of GBM cells induced by TMZ." (PMID 39443331, 2024). "Increased protein levels of MAP3K1 were found in glioma tissues compared with the para‐tumour tissue, especially in high‐grade glioma." (PMID 39443331, 2024). "GSEA analysis showed that DNA repair, homology directed repair, DNA mismatch and repair pathways were enriched in gliomas with high MAP3K1 expression." (PMID 39443331, 2024). "To explore the relationship between MAP3K1 and immune infiltration in glioma, we began by evaluating how MAP3K1 expression correlates with the presence of various immune cell types." (PMID 39443331, 2024). "Pathways including DNA repair, homology directed repair and DNA mismatch repair pathways were enriched in gliomas with high MAP3K1 expression." (PMID 39443331, 2024). "To provide more insight into the clinical significance of MAP3K1 expression in gliomas, we examined the MAP3K1 expression in glioma tissue from patients with varying survival outcomes, such as OS and disease‐free interval (DFI), using data from TCGA." (PMID 39443331, 2024). "Compared to normal tissue, glioma samples exhibiting MAP3K1 arm‐level deletions showed significantly increased infiltration of CD4+ T cells, neutrophils, and dendritic cells." (PMID 39443331, 2024). "The analysis of glioma patients with high MAP3K1 expression demonstrated poorer prognosis in the grade 3, 1p/19q codeletion and 1p/19q non‐codeletion groups." (PMID 39443331, 2024). "Similar results were obtained in glioma cells in which MAP3K1 silencing suppressed the migration of GBM cells." (PMID 39443331, 2024). "Immunohistochemical result showed that MAP3K1 knockdown combined with TMZ decreased the protein level of p‐ERK in intracranial glioma tissue." (PMID 39443331, 2024). "Subsequently, we utilized the receiver operating characteristic curve (ROC) to evaluate the ability of MAP3K1 in discerning between glioma samples and normal tissues." (PMID 39443331, 2024). "In present study, pathways including DNA repair, homology directed repair, platinum drug resistance, DNA mismatch and repair pathways were enriched in gliomas with high MAP3K1 expression." (PMID 39443331, 2024). "Using single‐cell RNA sequencing datasets, we performed t‐SNE analysis to determine the expression of MAP3K1 in glioma." (PMID 39443331, 2024). "KEGG pathway analysis demonstrated that mismatch repair and platinum drug resistance were enriched in gliomas with high MAP3K1 expression." (PMID 39443331, 2024). "We conducted pathway enrichment analysis of MAP3K1 in glioma to investigate its potential molecular mechanism." (PMID 39443331, 2024). "MAP3K1 was found to be highly expressed in high‐grade glioma, especially in GBM, according to the findings from the TCGA dataset." (PMID 39443331, 2024). "The results specifically indicated that the expression of MAP3K1 was notably elevated in glioma, which includes both GBM and low‐grade glioma (LGG)." (PMID 39443331, 2024). "Based on the public database, Xie and his colleagues identified MAP3K1 as a novel prognostic biomarker and potential therapeutic target in glioma." (PMID 36045691, 2022). "Expression of MAP3K1, as a target of let-7g-5p, has been enhanced by NEAT1, Therefore, NEAT1 enhances malignant features of glioma stem cell and chemoresistant phenotype via let-7g-5p/MAP3K1 axis." (PMID 34178658, 2021).
glioma (continued). "Next, combined overexpression of TRIB2 and MAP3K1 was identified in glioma and correlated with a poor prognosis of glioma with significant sensitivity and specificity." (PMID 31318172, 2020). "Overall, this study demonstrated the potential of TRIB2 and MAP3K1 as therapeutic targets in glioma." (PMID 31318172, 2020). "TRIB2 and MAP3K1 were identified as genes that are correlated with the pathology and survival of glioma." (PMID 31318172, 2020). "Survival data of 78 patients who received radiotherapy were extracted, and the Kaplan‐Meier analysis showed that high expression of TRIB2 and MAP3K1 was conversely correlated with the poor survival of patients with glioma who were treated with radiotherapy." (PMID 31318172, 2020). "Mitogen‐Activated Protein Kinase Kinase Kinase 1 (MAP3K1) is overexpressed in gliomas; however, its clinical significance, biological functions, and underlying molecular mechanisms remain unclear." (PMID 39443331, 2024). "Moreover, the level of MAP3K1 was higher in glioma patients over 60 years old compared with those under 60 years old." (PMID 39443331, 2024). "More work is needed to fully elucidate the role of MAP3K1 in glioma." (PMID 39443331, 2024). "The results of KEGG pathway analysis demonstrated that pathways, including the cell cycle, DNA replication, cellular senescence, mismatch repair, platinum drug resistance, glioma, PD‐L1 expression and the PD‐1 checkpoint pathway in cancer were enriched in gliomas with high MAP3K1 expression." (PMID 39443331, 2024). "MAP3K1 may play a likely role in regulating the antitumor immune response to promote the progression of glioma." (PMID 39443331, 2024). "While previous findings have suggested that MAP3K1 participates in the development of various tumour types, its precise role and gene expression pattern in glioma remain unclear." (PMID 39443331, 2024). "We conducted an additional evaluation of the predictive significance of MAP3K1 in glioma." (PMID 39443331, 2024). "The area under the curve (AUC) achieved by MAP3K1 was 0.885, suggesting that MAP3K1 might act as a biomarker and has a good capacity to separate glioma tissues from normal tissues." (PMID 39443331, 2024). "MAP3K1 was correlated with the immune infiltration in glioma." (PMID 39443331, 2024). "By IHC, we identified the levels of MAP3K1 protein in human glioma and para‐tumour tissues." (PMID 39443331, 2024). "The ROC analysis confirmed that the sensitivity and specificity of TRIB2/MAP3K1 expression were statistically significant, indicating that TRIB2/MAP3K1 expression should be investigated for evaluating the prognosis and therapeutic efficacy in patients with glioma." (PMID 31318172, 2020). "Moreover, co‐overexpression of TRIB2 and MAP3K1 (TRIB2High/MAP3K1High) tended to indicate shorter overall survival than other expression combinations in patients with glioma." (PMID 31318172, 2020). "Additionally, ROC analysis was performed to evaluate the sensitivity and specificity of TRIB2 and MAP3K1 for the prediction of outcomes in patients with glioma." (PMID 31318172, 2020). "These novel findings indicated that TRIB2 and MAP3K1 could be potential predictors for evaluating the survival and efficacy of routine adjuvant treatments of glioma." (PMID 31318172, 2020). "Overall, these data suggest that enriched TRIB2 and MAP3K1, which could be used to predict the efficacy of routine adjuvant treatment for glioma, may indicate increased resistance to TMZ and radiotherapy." (PMID 31318172, 2020). "TRIB2 and MAP3K1 could be used as novel therapeutic targets and prognostic biomarkers to evaluate the malignancy and long‐term outcome of glioma." (PMID 31318172, 2020). "Overall, our findings suggest that the combined increase in TRIB2 and MAP3K1 could be prognostic biomarkers and potential therapeutic targets for glioma." (PMID 31318172, 2020).